BCO1 (beta-carotene oxygenase 1)
Description:
Symmetrically cleaves beta-carotene into two molecules of retinal using a dioxygenase mechanism.
Synonyms: BCDO; BCDO1; BCMO1; FLJ10730; BCMO; BCO
Tractability: No criterion of Open Targets' tractability assessment is met for any kind of drug.
Gene: Protein-coding gene on chromosome 16 (81,238,576 to 81,291,226, forward strand). Ensembl gene ENSG00000135697.
Subcellular location: Cytoplasm, cytosol
Subcellular location (Human Protein Atlas): Actin filaments; Centriolar satellite
Pathways (Reactome):
Sensory Perception: Retinoid metabolism and transport
Gene Ontology:
Molecular function: beta-carotene 15,15'-dioxygenase activity; oxidoreductase activity, acting on single donors with incorporation of molecular oxygen, incorporation of two atoms of oxygen
Biological process: carotene catabolic process; retinal metabolic process; retinoid metabolic process; vitamin A biosynthetic process; isoprenoid metabolic process; retinol metabolic process
Cellular component: cytosol
Genetic constraint (gnomAD): Loss-of-function variants: 51 observed, 55.05 expected, observed/expected ratio (o/e) 0.93, 90% interval 0.74 to 1.17. The upper end of that interval is the gene's LOEUF score, 1.17, which puts it in group 5 of 6, group 1 being the genes least tolerant of losing a copy. Missense variants: 792 observed, 718.29 expected, observed/expected ratio (o/e) 1.1, 90% interval 1.04 to 1.17. Synonymous variants: 315 observed, 278.49 expected, observed/expected ratio (o/e) 1.13, 90% interval 1.03 to 1.24.
Homologues: Orthologues: chimpanzee BCO1 (99% identical), macaque BCO1 (97% identical), dog BCO1 (87% identical), mouse Bco1 (86% identical), pig BCO1 (84% identical), guinea pig BCO1 (84% identical), rat Bco1 (82% identical), rabbit BCO1 (70% identical), tropical clawed frog bco1 (65% identical), zebrafish bco1 (56% identical), Caenorhabditis elegans bcmo-1 (33% identical), Drosophila melanogaster ninaB (32% identical), and 1 more. Paralogues in human: BCO2 (38% identical), RPE65 (37% identical).
Diseases named in the same sentence as BCO1 in open-access papers:
BCO1 is named in the same sentence as 32 diseases in open-access papers, as found by Europe PMC text mining. Sharing a sentence is not in itself a finding about the gene and the disease. The quoted sentences say what the papers report.
vitamin A deficiency (6 papers, 2013 to 2024). Deficiency of vitamin A due to malnutrition, malabsorption, or dietary lack. "Similarly, HPLC measurements of plasma and hepatic vitamin A ruled out vitamin A deficiency in Bco1-/- mice baseline and resolution mice." (PMID 38319073, 2024). "Theoretically, vitamin A deficiency would increase the expression of SR-B1 and BCO1, which would facilitate an increase in lycopene absorption and possibly favor the central cleavage by BCO1 rather than by BCO2." (PMID 33668703, 2021).
Obesity (5 papers, 2009 to 2018). Accumulation of substantial excess body fat. "Loss of BCO1 expression has been linked to obesity and lipid metabolism and lipid accumulation in adipocytes by modulating PPARγ and RAR signaling pathways, although remains uncertain if BCO1 affects lipid metabolism in a similar manner in different tissues." (PMID 28732066, 2017).
atherosclerosis (4 papers, 2015 to 2024). A disease characterized by the build-up of fatty material and calcium deposition in the arterial wall resulting in partial or complete occlusion of the arterial lumen. "BCO1 activity is associated with the reduction of plasma cholesterol in humans and mice, while dietary β-carotene reduces hepatic lipid secretion and delays atherosclerosis progression in various experimental models." (PMID 38319073, 2024). "Our study shows that β-carotene promotes atherosclerosis resolution in two independent experimental models in a BCO1-dependent manner." (PMID 38319073, 2024). "In 2020, we confirmed the implication of BCO1 activity and vitamin A in the development of atherosclerosis." (PMID 38319073, 2024). "Our data show that the enzymatic activity of BCO1 mediates the bioactive actions of β-carotene in various preclinical models of obesity and atherosclerosis." (PMID 38319073, 2024). "Experiments in Bco1-/- mice implicate vitamin A production in the effects of β-carotene on atherosclerosis resolution." (PMID 38319073, 2024). "Dietary BC conversion to vitamin A retinoids through BCO1 decreases adiposity, circulating cholesterol, and atherosclerosis progression in various experimental animal models." (PMID 39684610, 2024). "Our data show that β-carotene favors atherosclerosis resolution in two independent mouse models, and results in Bco1-/- mice directly implicate vitamin A formation in this process." (PMID 38319073, 2024). "To test the contribution of BCO1 in macrophages in the progression of atherosclerosis, and whether these cells could rely on circulating β-carotene to form vitamin A in the atherosclerotic lesion, we performed a bone marrow transplant experiment." (PMID 39624361, 2024). "Lastly, we utilized Bco1-/- mice and CD25+ Treg depletion experiments in Foxp3EGFP mice to tease out the direct implications of vitamin A formation and Tregs on atherosclerosis resolution." (PMID 38319073, 2024).
dyslipidemia (3 papers, 2011 to 2022). "The GRS based on the three genetic variants of MARC1, ADCY5, and BCO1 has an additive risk effect for hypertriglyceridemia and suggest atherogenic dyslipidemia based on high triglycerides and low HDL-c levels in adult Mexican men." (PMID 36233117, 2022).
Hepatic steatosis (3 papers, 2011 to 2024). Steatosis is a term used to denote lipid accumulation within hepatocytes. "A connection of BC metabolism with metabolic health through the regulation of specific miRNAs in the liver is suggested by the fact that the ablation of key enzymes in carotenoid metabolism (BCO1 and BCO2) induces hepatic steatosis in mice by altering the farnesoid X receptor/miR-34a/sirtuin 1 axis." (PMID 39684610, 2024). "Additionally, emerging evidence suggests that BCO1 activity may counteract the development of hepatic steatosis and have other beneficial health effects independent of its role in carotenoid cleavage." (PMID 39684610, 2024).
lung carcinoma (3 papers, 2018 to 2023). "However, future human intervention studies are needed to identify role of BCO1/BCO2 genotypes in lung cancer development and establish dietary recommendations for carotenoids." (PMID 36771049, 2023). "Therefore, assessing BCO1 genotypes in participants who developed lung cancer in the β-carotene supplementation study is needed to test whether the BCO1 genotype also modulates lung cancer incidence." (PMID 35571879, 2022).
neuroblastoma (3 papers, 2020 to 2024). Neuroblastoma (NB) is the most common solid, extracranial childhood tumor. "Interestingly, BCO1 was recently described to inhibit the metastatic potential of cancer neuroblastoma cells by regulating differentiation-related miRNAs." (PMID 39684610, 2024). "Interestingly, the enzyme β-carotene 15,15′-oxygenase (BCO1) catalyzes the first step of the biosynthesis of vitamin A, which is important for neuroblastoma differentiation." (PMID 33321708, 2020). "However, there was also evidence that BCO1 is stably expressed in NB cells, and the expression of this gene inhibits the self-renewal and labeling of neuroblastoma CSC by regulating related miRNA." (PMID 32547947, 2020).
chronic lung disease (1 paper, 2017). According to the definitions of the American and British Thoracic Societies, including pulmonary functional tests, X-rays, and CT scans for items such as fibrosis, bronchiectasis, bullae, emphysema, nodular or lymphomatous abnormalities. "DEX-mediated inhibition of BCO1 sheds light on how glucocorticoids can antagonize the effects of retinoids in alveolarization and lipid metabolism during development and in chronic lung diseases." (PMID 28732066, 2017).
colon cancer (1 paper, 2021). "Using the CellExpress tool, we searched BCO1 expression levels in the Sanger Cell Line Project dataset and found that the expression level in THP-1 cells would be almost the same level as in LoVo colon cancer cells, which were demonstrated to express functional BCO1." (PMID 34835955, 2021).
hypertriglyceridemia (1 paper, 2022). A laboratory test result indicating elevated triglyceride concentration in the blood. "We added the rs6564851 SNP on the BCO1 gene to the GRS model because, recently, we reported a significant association between this variant with the risk for hypertriglyceridemia in a group of middle-aged Mexican adult men." (PMID 36233117, 2022). "Interestingly, our results suggest an aggregate effect between the MARC1, ADCY5, and BCO1 for hypertriglyceridemia, and the effect appears to be exclusive for men." (PMID 36233117, 2022).
hypervitaminosis A (1 paper, 2021). A symptom complex resulting from ingesting excessive amounts of vitamin A. "Excessive intake of BC does not cause hypervitaminosis A but carotenemia (BC accumulation), as its conversion to retinoids by the enzyme β-carotene oxygenase-1 (BCO1) is regulated by enterocytes of the intestine to maintain an optimum level of vitamin A." (PMID 33631212, 2021).
lung adenocarcinoma (1 paper, 2017). A carcinoma that arises from the lung and is characterized by the presence of malignant glandular epithelial cells. "In the present study, we have investigated the metabolism of β-carotene by BCO1 and the effect of GC treatment on the BCO1 expression in A549 cells, a human lung adenocarcinoma-derived cell line exhibiting alveolar epithelial properties." (PMID 28732066, 2017).
pancreatitis (1 paper, 2020). Inflammation of the pancreas. "Since lycopene may be cleaved by both BCO1 and BCO2, the inhibitory effect of lycopene on the development of pancreatitis may be contributed by intact lycopene and/or its metabolites." (PMID 32806545, 2020). "Since rodent models do not accumulate carotenoids, including lycopene, mutant animal models that are BCO1-/- and BCO2-/- may be useful to determine the biological activity as well as the interaction of lycopene with lipid mediators in the pathogenesis of pancreatitis." (PMID 32806545, 2020).
prostate carcinoma (1 paper, 2020). A carcinoma that arises from epithelial cells of the prostate gland. "We used univariate and multivariate Cox regression analysis to identify seven prognostic signatures for prostate cancer patients, including BCO1, BAIAP2L2, C7, AP000844.2, ASB9, MKI67P1, TMEM272." (PMID 32547947, 2020).
cancer (2 papers, 2017 to 2024). A tumor composed of atypical neoplastic, often pleomorphic cells that invade other tissues. "For example, administration of 3-keto-HPR instead of fenretinide may be preferential if inhibition of SCD1 or DES1 activity is the goal (cancer), while MPR may be better for BCO1 modulation (carotenoid metabolism)." (PMID 28448568, 2017).
BCO1 also shares sentences with these, for which no sentence is quoted: age-related macular degeneration (1 paper); asthma (1); Blindness (1); cholestasis (1); colorectal carcinoma (1); coronary heart disease (1); diabetes mellitus (1); endocrinopathies (1); hemochromatosis (1); hepatoma (1); Infertility (1); microphthalmia (1); myopia (1); nephrosis (1); retinal disease (1); type 1 diabetes (1); type 2 diabetes (1).